HIF1A (hypoxia inducible factor 1 subunit alpha)
Diseases named in the same sentence as HIF1A in open-access papers (continued):
Sharing a sentence is not in itself a finding about the gene and the disease.
amyloid (4 papers, 2020 to 2025). "Furthermore, the involvement of HIF-1α has also been well-documented in amyloidosis associated with AD." (PMID 34527417, 2021). "Additionally, the involvement of hypoxia-induced HIF-1α has been well documented in amyloidosis associated with AD." (PMID 32453744, 2020). "Gene silencing approaches confirmed the regulatory role of HIF-1α in BACE1 mediated amyloidosis leading to astrocyte activation and neuroinflammation." (PMID 34527417, 2021). "In keeping with our published findings with HIV Tat, morphine also induced amyloidosis and upregulated the expression of HIF-1α in HPAs both transcriptionally as well as translationally." (PMID 34527417, 2021). "Gene silencing approaches confirmed the regulatory role of HIF-1α in BACE1-AS/BACE1 in Tat-mediated amyloidosis." (PMID 32453744, 2020). "Another striking difference noted between Tat-mediated amyloidosis in neurons versus astrocytes is the unique involvement of HIF-1α and PHD-2 in astrocytes versus the neurons." (PMID 32453744, 2020). "Silencing of PHD-2 up-regulated HIF-1α–mediated amyloidosis and, in contrast, overexpressing PHD-2 mitigated this process." (PMID 32453744, 2020). "The present study for the first time identifies the role of astrocytes in HIV-1 Tat–mediated amyloidosis, with the involvement of the HIF-1α–lncRNA BACE1-AS complex in this process." (PMID 32453744, 2020). "The role of HIF-1α and BACE1-AS in HIV-1 Tat–induced amyloidosis, however, remains unexplored." (PMID 32453744, 2020). "Dysregulation of both HIF-1α expression and the downstream pathways in response to hypoxia induces motor neuron degeneration in ALS, and stimulates the production of β-amyloid peptides and the accumulation of amyloid plaques in AD." (PMID 33126586, 2020).
aortic aneurysm (4 papers, 2015 to 2023). A ruptured aneurysm located in the wall of the proximal portion of the descending aorta proceeding from the arch of the aorta. "Such upregulation translated into higher hypoxia-inducible factor 1 (HIF-1) and vascular endothelial growth factor A (VEGF-A) expression and dysregulated HIF-1α/VEGF signaling was associated with aortic aneurysm progression." (PMID 34572356, 2021). "Since dysregulation of the Hif-1α/Vegfa and Tgfb1/Ctgf pathways has been linked to aortic aneurysm progression, these Nox4 target genes likely contribute to aortic pathology in PKG1RQ/+ mice." (PMID 31387997, 2019). "NOX4 upregulation leads to increased Hif-1α and Vegfa expression, and dysregulated HIF-1α /VEGF signaling has been observed in TAAD and linked to aortic aneurysm progression." (PMID 31387997, 2019). "The expression of HIF-1α is significantly higher in aortic aneurysms than in normal arteries, with increased nuclear translocation, implicating HIF-1α in AAA progression." (PMID 25964891, 2015).
autoimmune uveitis (4 papers, 2022 to 2025). An autoimmune form of uveitis (disease). "Hif1α identified as a potential participant in autoimmune uveitis pathogenesis by regulating Th-17, Th1, and regulatory T cells." (PMID 40867565, 2025). "In experimental autoimmune uveitis models, Irisin has been shown to modulate microglial polarization and mitigate disease severity by suppressing Th1 and Th17 cells responses, as well as reducing M1 microglial polarization through the HIF-1α signaling pathway (Wang MQ." (PMID 40365310, 2025).
bladder tumors (4 papers, 2016 to 2024). "The lncRNA urothelial carcinoma-associated 1 (UCA1) is involved in bladder tumor progression and identified as an oncogenic HIF1A target gene." (PMID 35659268, 2022). "Considering the essential role of IFN-γ in anti-tumor responses, we evaluated the ability of Hif1α–/– T cells to kill tumor cells by co-culturing pre-activate WT or Hif1α–/– hypoxic T cell with MB49 bladder tumor cells at a ratio of 2:1." (PMID 39477954, 2024). "Indeed, we observed upregulation of HIF-1α in human bladder tumor samples, together with VEGF (angiogenesis) and IL-1α and IL-1β (inflammation), which are indicative of poor prognosis in cancer and aggressiveness." (PMID 36233054, 2022).
cardiac arrest (4 papers, 2024 to 2025). Cessation of breathing and/or cardiac function. "Experimental evidence showed increased HIF-1α expression 1 h after systemic hypoxia due to cardiac arrest, elevated levels over 12 h, and persistence for at least 7 d after transient global cerebral ischemia." (PMID 40141795, 2025). "High levels of O2 eliminated HIF-1α nuclear staining induced by cardiac arrest, while NICD was still absent in the AVC endocardium." (PMID 39932433, 2025). "The fact that no nuclear Hif1α expression was observed in the LV after cardiac arrest despite the increased MDR1 expression after 1–4 days of reperfusion is likely due to the very short half-life (~ 5–8 min) of Hif1α after return to normal oxygen levels." (PMID 38902373, 2024).
chronic bronchitis (4 papers, 2015 to 2023). A type of chronic obstructive pulmonary disease characterized by chronic inflammation in the bronchial tree that results in edema, mucus production, obstruction, and reduced airflow to and from the lung alveoli. "BEAS-2B showed a small but significant increase of VEGF-A after hypoxia exposure, which is in line with previous studies with increased expression of VEGF and HIF-1α in lung tissue from patients with chronic bronchitis." (PMID 36994416, 2023). "In patients with a prolonged history of smoking, combined with chronic bronchitis, there is a significant increase of HIF1α and vascular endothelial growth factor (VEGF) in the vascular endothelium and smooth muscle cells (SMCs), compared to the smokers without chronic bronchitis." (PMID 32708482, 2020). "It has been reported that HIF-1α is up-regulated in the airways of patients with COPD and chronic bronchitis." (PMID 25851169, 2015).
Chronic Sinusitis (4 papers, 2014 to 2025). "Previous reports have linked smoking to sinusitis, suggesting that smoking induces an inflammatory response in the nasal mucosa, resulting in tissue hypoxia that may promote HIF-1α expression." (PMID 41346909, 2025). "The results indicate that anoxia up-regulates MUC5AC by the HIF-1α signaling pathway in human nasal epithelia and suggest that hypoxia might be a pathogenic mechanism of mucus hypersecretion in sinusitis." (PMID 24840724, 2014). "In the specimens from sinusitis patients, over-expression of HIF-1α and MUC5AC was observed by immunohistochemistry." (PMID 24840724, 2014). "Strong expression of HIF-1α was also noted in immunohistochemical analysis of epithelium from sinusitis." (PMID 24840724, 2014). "The expression of HIF-1α was also determined in sinusitis patients." (PMID 24840724, 2014). "Therefore, increasing the oxygen tension in the sinus may result in improvement in sinusitis by reducing MUC5AC production, and modulation of HIF-1α activity should be considered as a new target for the treatment of sinusitis." (PMID 24840724, 2014). "In human sinusitis mucosa, which is supposed to be hypoxic, expression of MUC5AC and HIF-1α is higher than in control mucosa." (PMID 24840724, 2014).
clear cell carcinoma (4 papers, 2005 to 2021). "A frequent finding in the majority of conventional clear cell carcinomas is a mutation in the von Hippel-Lindau (VHL) suppressor gene, the protein product of this gene is required for degradation of hypoxia-inducible factor 1α (HIF-1α)." (PMID 16222313, 2005). "Five most downregulated genes in clear cell carcinoma include, ITGB6 (−9.09-fold), MUC1 (−5.00-fold), CDH1 (−3.57-fold), HIF1A (−2.27-fold) and FOS (−1.96-fold)." (PMID 30863721, 2019). "Increased lipid unsaturation might correlate with HILPDA activation as HIF1α/2α was shown to significantly enrich polyunsaturated lipids via HILPDA in clear-cell carcinomas, independent of its ATGL-suppressing function." (PMID 34277635, 2021). "As Caki-1 and SKRC44 cells are each derived from clear cell carcinomas, the high Epo and EpoR expression levels may be either dependent or independent of HIF-1α in clear cell carcinoma cell lines." (PMID 23833638, 2013).
cognitive decline (4 papers, 2014 to 2025). "Particularly, the oxygen responsive HIF-1α subunit may significantly contribute to the cognitive decline by influencing some mechanisms associated with APP amyloidogenic metabolism." (PMID 27294139, 2016). "Thus alterations of oxygen responsive HIF-1α subunit in the central nervous system may contribute to the cognitive decline, especially influencing mechanisms associated to amyloid precursor protein (APP) amyloidogenic metabolism." (PMID 24478626, 2014). "The experimental groups treated with linagliptin or saxagliptin showed a reduction in the degradation of both HIF1α and BDNF, NT4, leading to decreased cognitive decline compared to the diabetic mice." (PMID 38860903, 2025).
dry eye (4 papers, 2016 to 2024). "Interestingly, in a HIF-1α conditional knockout mouse model with dry-eye, the lacrimal glands exhibited increased acinar cell apoptosis and loss of glandular structures and polarities, and the blockage of HIF-1α COX-2 axis enhanced inflammation." (PMID 28484714, 2017). "Conversely, in a HIF-1α conditional knockout mouse model with dry-eye, the lacrimal glands exhibited increased acinar cell apoptosis and loss of glandular structures and polarities and, on the other hand, the blockage of HIF-1α COX-2 axis enhanced inflammation." (PMID 28484714, 2017). "In SS dry eye patients, upregulation of HIF-1α can activate the autophagy pathway, prevent damage to lacrimal acinar cells, and maintain normal lacrimal gland function." (PMID 39575238, 2024). "In the context of dry eye, upregulation of HIF-1α in SS patients can activate the autophagy pathway." (PMID 39575238, 2024). "Wild-type mice with DED exhibited less damage to their secretory structures and minor loss of LG polarities and morphologies when compared with HIF-1α-knockout mice with DED, indicating the depletion of HIF-1α in preventing dry eye–induced acinar cell death in the LG." (PMID 37108146, 2023). "By using hypoxia-inducible factor-1 alpha conditional knockout (HIF-1α CKO) mice and a dry eye (DE) mouse model, we aimed to determine the role played by delta-like ligand 4 (Dll4)/Notch signaling and HIF-1α in the lymphangiogenesis of lacrimal glands (LGs)." (PMID 26828208, 2016).
Ductal Carcinoma (4 papers, 2002 to 2013). "In our study, we confirm the association of HIF-1α and Ki67 expression, both by pairwise correlation and similar factor loadings on the factor 1 (i-Grade) in the group of ductal carcinoma." (PMID 22424533, 2012). "Second, in the group of HR-positive ductal carcinoma, HIF-1α participates in the most important factor 1 along with SATB1 providing factor loadings opposite to those of AR, ER and BCL2, independently of Ki67 expression (factor 3)." (PMID 22424533, 2012). "In the group of ductal carcinoma, we find that HIF-1α participates in two factors: factor 1 (i-Grade) along with Ki67 and factor 2 - along with SATB1." (PMID 22424533, 2012). "First, in the group of ductal carcinoma, we find that HIF-1α participates in two factors: factor 1 (i-Grade) along with Ki67 and factor 2 - along with SATB1." (PMID 22424533, 2012). "Nevertheless, it is remarkable that SATB1 was closely associated with HIF-1α in HR-positive and the whole cohort of ductal carcinoma; the factors with involvement of SATB1 and HIF-1α caused a major portion of variation in both groups, especially, in HR-positive tumours." (PMID 22424533, 2012).
ductal carcinoma in situ (4 papers, 2012 to 2023). "The plasma level of HIF-1α in the invasive cancer group was higher than in ductal carcinoma in situ (DCIS) group." (PMID 27780920, 2016). "In large ductal carcinoma in situ patient-specimens, we find that epithelial cells with high HIF-1α levels and multiple cell layers away from the vasculature are immature compared to well-oxygenated cells." (PMID 23029547, 2012). "HIF1α could be mainly observed in tumor hypoxic core necrotic regions, and was overexpressed in some precursor lesions such as ductal carcinoma in situ (DCIS)." (PMID 36967443, 2023).
endometrial adenocarcinoma (4 papers, 2013 to 2020). "Recently, one report presents that exclusive cytoplasmic localization of Foxp1 in endometrial adenocarcinoma is linked with deep myometrial invasion mediated by HIF-1α, which is an essential player in cellular and systemic responses to hypoxia." (PMID 26171970, 2015). "Previous reports have shown that HIF-1α and its downstream gene GLUT1 are increasingly expressed from normal to endometrial hyperplasia, further to endometrial adenocarcinoma." (PMID 32548315, 2020).
enteritis (4 papers, 2019 to 2024). Inflammation of the small intestine. "Simultaneously, our study also suggests that IEC-derived Hif1-α may represent a master regulator of enteritis and intestinal microbiota." (PMID 31040849, 2019). "A previous study showed that endothelial-specific deletion of HIF-1α protects against radiation-induced enteritis, whereas epithelial-specific deletion of HIF-1α does not." (PMID 39585307, 2024).
Fibroadenoma (4 papers, 2005 to 2025). A benign tumor of the breast characterized by the presence of stromal and epithelial elements. "In contrast to phyllodes tumors, HIF-1α seems of minor relevance in the tumorigenesis of fibroadenomas." (PMID 16168127, 2005). "Only two fibroadenomas with low-level stromal HIF-1α immunoreactivity (1% and 2% positive nuclei) were found without concerted CAIX expression." (PMID 16168127, 2005). "We only found two fibroadenomas with low-level expression of HIF-1α in the stroma, in agreement with Zhong and colleagues, who found all their fibroadenomas to be negative." (PMID 16168127, 2005). "We studied the expression and prognostic relevance of HIF-1α and its downstream targets in phyllodes tumors and fibroadenomas of the breast." (PMID 16168127, 2005). "The fibroadenomas with stromal HIF-1α positivity were microscopically inconspicuous, however." (PMID 16168127, 2005). "Expression of FGF, PDGF and transforming growth factor beta have been described in fibroadenomas and may contribute to HIF-1α-independent expression of VEGF." (PMID 16168127, 2005). "In five fibroadenomas and 10 phyllodes tumors, of which five had stretches of HIF-1α-positive epithelium, the mean shortest distance between microvessels and the epithelial basal membrane was 50 ± 11 μm for fibroadenomas and was 83.3 ± 16 μm for phyllodes tumors (P = 0.005)." (PMID 16168127, 2005). "Perhaps positive stromal HIF-1α staining in a fibroadenoma may reflect an increased intrinsic capacity to progress to phyllodes tumor." (PMID 16168127, 2005). "KRT5, TGF-β, PAI-1, HIF-1α, TIMP1, MMP2, TWIST1, VEGFα, and BRCA2 were all significantly upregulated in fibroadenomas." (PMID 40806434, 2025). "The qPCR results exhibited that the expression level of HIF-1α and CD147 in TNBC tissue was significantly higher than that in breast fibroadenoma tissue." (PMID 38847725, 2024). "We therefore studied expression of HIF-1α and its downstream targets VEGF and CAIX in breast phyllodes tumors of various grades and in fibroadenomas." (PMID 16168127, 2005). "Only two fibroadenomas displayed low-level stromal HIF-1α reactivity in the absence of CAIX expression." (PMID 16168127, 2005). "On the other hand, HIF-1α and CAIX seem to be of minor relevance in breast fibroadenomas." (PMID 16168127, 2005). "Since only two fibroadenomas displayed low-level stromal HIF-1α immunoreactivity and none expressed CAIX, HIF-1α and CAIX seem to be of little relevance in these tumors." (PMID 16168127, 2005).
gastrointestinal stromal tumor (4 papers, 2010 to 2020). "For example, succinate accumulates in succinate dehydrogenase-deficient tumors like gastrointestinal stromal tumors (GIST), inhibits prolyl hydroxylase activity with subsequent HIF-1α stabilization and therefore drives cancer progression." (PMID 28061458, 2017).
giant cell tumor (4 papers, 2010 to 2020). A benign, intermediate, or malignant tumor that arises from the bone or soft tissue. "It is reported that miR-210 was upregulated by HIF-1α in the stromal cells of giant cell tumors of bone." (PMID 33344235, 2020).
gout (4 papers, 2014 to 2024). A condition characterized by painful swelling of the joints, which is caused by deposition of urate crystals. "Furthermore, there was a significant reduction of oxygen consumption and an obvious increment of HIF-1α expression in the intestine of gout mice, which further confirmed that the alteration of gut microbiota and intestinal metabolic phenotype associated with the development of gout." (PMID 33603667, 2020). "Some signatures of metabolome in male gout patients have been reported being involving in inflammation, such as acetate that regulates T cells, IL-8, TNF-α and 1L-1β through binding GPR43, succinate that induces IL-1β through HIF-1α and glucose that regulates T cell activation." (PMID 28270806, 2017).
hearing loss (4 papers, 2021 to 2023). "Previous studies on hearing loss have revealed that HIF-1α is a master regulator of the cellular adaptive response to hypoxia." (PMID 35096971, 2021).
hemorrhagic stroke (4 papers, 2017 to 2023). A stroke caused by a bleed on the brain. "Serum HIF‐1α is a better biomarker in diagnosing IS patients but further work in larger groups, including those with hemorrhagic stroke is necessary to confirm its diagnostic utility." (PMID 34708885, 2021). "These genes encode hemoglobin and HIF-1α etc. and might be potential biomarkers of hemorrhagic stroke." (PMID 33123006, 2020). "The MDA contents were significantly reduced and SOD activities were significantly increased after intra-thalamic injection of YC-1 and MCC950, implying that blocking HIF-1α and NLRP3 suppressed the oxidative stress induced by thalamic hemorrhagic stroke." (PMID 36944982, 2023). "Next, we investigated the role of HIF-1α and NLRP3 in the inflammatory cascade and oxidative stress after thalamic hemorrhagic stroke by analyzing the expression of several pro-inflammatory cytokines and two key oxidative stress markers, MDA and SOD." (PMID 36944982, 2023). "In the present study, we found that the protein level of HIF-1α was significantly increased at the early phase, but not in the late phase, after hemorrhagic stroke induced by ITC." (PMID 28785202, 2017). "Hypoxia inducible factor 1α (HIF-1α), a transcription factor which is closely related to the expression of SDF1 and CXCR4 under hypoxia condition, has been observed to be significantly up-regulated following ITC-induced hemorrhagic stroke." (PMID 28785202, 2017).
hepatoblastoma (4 papers, 2015 to 2023). Hepatoblastoma (HB) is a malignant hepatic tumor and is the most common pediatric liver cancer. "In hepatoblastoma and HCC cell lines, HepG2, Hep3B, and Huh-7, we confirmed the expression of hypoxia-inducible factor (HIF)-1α, an accelerator of tumor aggressiveness and the inflammatory response." (PMID 37511305, 2023).